DGKH (diacylglycerol kinase eta)
Description:
Diacylglycerol kinase that converts diacylglycerol/DAG into phosphatidic acid/phosphatidate/PA and regulates the respective levels of these two bioactive lipids. Thereby, acts as a central switch between the signaling pathways activated by these second messengers with different cellular targets and opposite effects in numerous biological processes (Probable). Plays a key role in promoting cell growth. Activates the Ras/B-Raf/C-Raf/MEK/ERK signaling pathway induced by EGF. Regulates the recruitment of RAF1 and BRAF from cytoplasm to membranes and their heterodimerization.
Synonyms: DGKeta
Tractability: Antibody: UniProt places it where antibodies can reach, with high confidence; its Gene Ontology location is reachable by antibodies, with high confidence; the Human Protein Atlas places it where antibodies can reach. PROTAC: ubiquitination databases record sites on it; its protein half-life has been measured.
Target class: Enzyme; Transferase
Gene: Protein-coding gene on chromosome 13 (42,040,036 to 42,256,578, forward strand). Ensembl gene ENSG00000102780.
Subcellular location: Cytoplasm; Cell membrane
Subcellular location (Human Protein Atlas): Plasma membrane; Vesicles
Pathways (Reactome):
Hemostasis: Effects of PIP2 hydrolysis
Gene Ontology:
Molecular function: ATP-dependent diacylglycerol kinase activity; protein binding; kinase activity
Biological process: diacylglycerol metabolic process; phosphatidic acid metabolic process; phospholipase C/protein kinase C signal transduction; positive regulation of 1-phosphatidyl-1D-myo-inositol 4,5-bisphosphate biosynthetic process; intracellular signal transduction; lipid phosphorylation; phosphatidic acid biosynthetic process; platelet activation; glycerolipid metabolic process; phospholipase C-activating G protein-coupled receptor signaling pathway; signal transduction
Cellular component: cytoplasm; endosome; plasma membrane; actin cytoskeleton
Genetic constraint (gnomAD): Loss-of-function variants: 76 observed, 133.48 expected, observed/expected ratio (o/e) 0.57, 90% interval 0.47 to 0.69. The upper end of that interval is the gene's LOEUF score, 0.69, which puts it in group 2 of 6, group 1 being the genes least tolerant of losing a copy. Missense variants: 1,120 observed, 1,405.5 expected, observed/expected ratio (o/e) 0.8, 90% interval 0.76 to 0.84. Synonymous variants: 520 observed, 523.47 expected, observed/expected ratio (o/e) 0.99, 90% interval 0.92 to 1.07.
Homologues: Orthologues: chimpanzee DGKH (99% identical), macaque DGKH (99% identical), dog DGKH (96% identical), rabbit DGKH (93% identical), rat Dgkh (91% identical), pig DGKH (90% identical), guinea pig DGKH (88% identical), mouse Dgkh (86% identical), tropical clawed frog dgkh (79% identical), zebrafish dgkh (76% identical), Drosophila melanogaster CG34384 (49% identical), Caenorhabditis elegans dgk-4 (30% identical), and 2 more. Paralogues in human: DGKD (64% identical), DGKK (38% identical), DGKI (20% identical), DGKG (20% identical), DGKB (19% identical), DGKQ (19% identical), DGKA (19% identical), DGKZ (19% identical), DGKE (16% identical).
Diseases named in the same sentence as DGKH in open-access papers:
DGKH is named in the same sentence as 36 diseases in open-access papers, as found by Europe PMC text mining. Sharing a sentence is not in itself a finding about the gene and the disease. The quoted sentences say what the papers report.
bipolar disorder (7 papers, 2007 to 2025). A disorder of the brain that causes unusual shifts in mood, energy, activity levels and the ability to carry out day-to-day tasks. "The present study identified a significant association between NPY-LA and DGKH, a gene that has previously been reported in bipolar disorders." (PMID 35627254, 2022). "This DGKH risk haplotype was previously shown to be associated with bipolar disorder, but also with major depression and adult ADHD, and was observed to have functional effects on brain volume and peripheral gene expression." (PMID 32377792, 2020). "Our group found that a different polymorphism, also located in the first intron of DGKH gene, was significantly associated with bipolar disorder in Hong Kong Chinese." (PMID 27386253, 2016). "He carries a risk genotype (G/C) in rs77072822 which lies in the first intron of DGKH gene that was mostly reported to be associated with bipolar disorder." (PMID 26120503, 2015). "He carries a risk genotype in rs77072822 which lies in the first intron of DGKH gene that was mostly reported to be associated with bipolar disorder." (PMID 26120503, 2015). "Similarly, we have obtained as top-ranked in this population the DGKH gene, which is a well-known gene for bipolar disorders but is also associated with personality traits in some studies." (PMID 41374081, 2025). "Moreover, several polymorphisms or haplotypes in the first intron of DGKH (diacylglycerol kinase eta) gene were reported to be associated with bipolar disorder in Caucasians and Chinese." (PMID 27386253, 2016). "This study illustrated that a 16-year-old boy with hypomania symptoms responded well to supplementation of phosphatidylcholine and the boy carries a risk genotype in DGKH gene for bipolar disorder, which provides a possible explanation for the boy’s beneficial effect at the genetic level." (PMID 26120503, 2015). "Subsequently, Zeng and colleagues also confirmed that DGKH was associated with bipolar disorder in a Chinese Han population including 1139 unrelated bipolar disorder patients and 1138 ethnically matched healthy controls using a tagging single nucleotide polymorphisms (SNPs) strategy." (PMID 26120503, 2015). "The “no call” signal- rs9532989 in sequencing data and its nearby SNPs in the same LD block with rs9532989 in the first intron of DGKH were chosen to carry out the association study of bipolar disorder in an age and gender-matched Hong Kong Chinese cases and controls." (PMID 26120503, 2015). "This SNP marker that we found to be associated with bipolar disorder is a novel marker that has not been reported in previous studies, although it is located in the same region, i.e. the first intron of DGKH, which was mostly reported to be associated with bipolar disorder." (PMID 26120503, 2015). "Following this observation, we aimed to investigate whether the potential beneficial effect of phosphatidylcholine supplementation was associated with the fact that the boy carries susceptibility variants in the first intron of DGKH for bipolar disorder." (PMID 26120503, 2015). "While inactivation of Dgkh in mice increases levels of dopamine in the midbrain, variants of DGKH were associated with ADHD and bipolar disorder." (PMID 37542675, 2023). "Diacylglycerol kinase eta (DGKH), encoding an important member of DGK enzymes family, has been reported associating with bipolar disorder in a genome-wide association study (GWAS) and replicated in Chinese Han population." (PMID 26120503, 2015). "SNP-MaP has been used as an initial screen in the identification of four susceptibility loci for mild mental impairment, 11 SNPs associated with reading ability, and several SNPs, including an intronic SNP from the diacylglycerol kinase eta (DGKH) gene, associated with bipolar disorder." (PMID 17610740, 2007).
nephrolithiasis (5 papers, 2012 to 2022). The presence of a calculus in the pelvis of the kidney; this is most often composed of mineral salts and proteins. "In addition, DGKH is associated with the formation of kidney stones by affecting calcium sensitive receptor (CasR) signaling and calcium metabolism in the body." (PMID 36482994, 2022). "A recent meta-analysis identified 20 nephrolithiasis-associated loci, including CYP24A1, DGKD, DGKH, WDR72, GPIC1, and BCR locus which were predicted to affect vitamin D metabolism and calcium-sensing receptor signaling respectively." (PMID 35439979, 2022). "Here we found three novel loci for nephrolithiasis: RGS14-SLC34A1-PFN3-F12 on 5q35.3 (rs11746443; P = 8.51×10−12, odds ratio (OR) = 1.19), INMT-FAM188B-AQP1 on 7p14.3 (rs1000597; P = 2.16×10−14, OR = 1.22), and DGKH on 13q14.1 (rs4142110; P = 4.62×10−9, OR = 1.14)." (PMID 22396660, 2012).
major depression (2 papers, 2020 to 2025). "Of particular interest, diacylglycerol kinase eta (Dgkh), which was down-regulated in the PFC, has been linked to bipolar disorder, unipolar depression, ADHD, and panic disorder." (PMID 41002437, 2025).
mental disorder (2 papers, 2015 to 2020). A disease that has its basis in the disruption of mental process. "In particular, DGKH is reported to be associated with other mental disorders, and further clinical applications are expected." (PMID 32388794, 2020). "Recent studies indicated that supplementation of phosphatidylcholine has been found to be beneficial for psychiatric diseases and Diacylglycerol Kinase, Eta (DGKH) protein was involved in regulating the metabolism of phosphatidic acid and diacylglycerol." (PMID 26120503, 2015). "Moreover, the role of DGKH in mental disorder was further confirmed from data obtained in animal studies." (PMID 26120503, 2015).
acute monocytic leukemia (1 paper, 2023). Acute monoblastic leukemia (AML-M5), is one of the most common subtypes of acute myeloid leukemia (AML) that is either comprised of more than 80% of monoblasts (AML-M5a) or 30-80% monoblasts with (pro)monocytic differentiation (AML-M5b). "DGKH consistently showed the lowest expression except in acute monocytic leukemia (AMOL), while DGKZ, DGKD, DGKQ and DGKA exhibited the highest expression levels." (PMID 37509516, 2023).
Calcium oxalate nephrolithiasis (1 paper, 2017). The presence of calcium- and oxalate-containing calculi (stones) in the kidneys. "In 2014, an association study of DGKH genetic polymorphisms with calcium oxalate nephrolithiasis has been performed in Chinese population, and their findings also implicate a link between nucleotide variant of DGKH and nephrolithiasis." (PMID 28361944, 2017).
colon cancer (1 paper, 2023). "Western blot assays revealed that forced LINC01138 expression in colon cancer cells SW480 increased the expression of diacylglycerol kinase eta (DGKH) and Phosphodiesterase 4D (PDE4D), whereas resulted in decrease the expression of pyrroline‐5‐carboxylate reductase 1 (PYCR1) and transketolase (TKT)." (PMID 36366731, 2023).
coronary artery disease (1 paper, 2024). "Polymorphisms in genes associated with the regulation of calcium levels (CASR, CYP24A1, CARS, DGKD, DGKH/KIAA0564 and GATA3) and metalloproteinases (MMP-3 and MMP-9) were also associated with an increased risk of coronary artery disease and AMI." (PMID 38478535, 2024).
COVID-19 (1 paper, 2023). A disease caused by infection with severe acute respiratory syndrome coronavirus 2. "The DGKH gene has been identified previously as differentially expressed in sarcoidosis; however, it has not been found in association with severe COVID-19." (PMID 36785619, 2023).
Insulin resistance (1 paper, 2025). Increased resistance towards insulin, that is, diminished effectiveness of insulin in reducing blood glucose levels. "DGKH, enriched in diacylglycerol(DAG) metabolism (GO:0046339), glycerolipid metabolism (GO:0006650), and PI signaling (hsa04070), regulates lipid balance and mitigates DAG-induced insulin resistance." (PMID 41208460, 2025).
melanoma (1 paper, 2023). A malignant, usually aggressive tumor composed of atypical, neoplastic melanocytes. "DGKH was significantly upregulated in tumor-infiltrating CD8+ T cells in melanoma and SCC in our study." (PMID 38023136, 2023).
mood disorder (1 paper, 2014). A cognitive disorder a disturbance in which the person's mood is hypothesized to be the main underlying feature. "Four of the most consistently replicated variants associated with mood disorder occur in genes important for synaptic function: ANK3 (rs10994336), BDNF (rs6265), CACNA1C (rs1006737), and DGKH (rs1170191)." (PMID 24944871, 2014).
Obesity (1 paper, 2021). Accumulation of substantial excess body fat. "Additionally, other causal genes are highly expressed or known to act in human brain function (i.e., NEGR1, GNPDA2, CYP46A1, DGKH) and various carcinomas (i.e., PMAIP1, HORMAD1, FES, BCAS3), indicating the potential role of metabolic dysregulation in the pathogenesis of obesity and cardiac events." (PMID 33910581, 2021).
osteoporosis (1 paper, 2022). A condition of reduced bone mass, with decreased cortical thickness and a decrease in the number and size of the trabeculae of cancellous bone (but normal chemical composition), resulting in increased fracture incidence. "Target genes with the highest number of miRNAs were DGKH, TNRC6B, ZNF704, INO80D and NFAT5, but according to the literature, none of these were ever directly associated with PTH or osteoporosis." (PMID 36011354, 2022).
ovarian carcinoma (1 paper, 2018). A malignant neoplasm originating from the surface ovarian epithelium. "In the ovarian cancer patients with taxol adjuvant therapy, the other DGKH, except probes 227415_at and 1553300_a_at, and MFSD6 microarray probes displayed similar prognostic significance under PFS probability." (PMID 30301218, 2018). "Under the condition of progression-free survival (PFS) probability, we found that FBXL7 and MFSD6 transcripts at high levels—but DGKH at low levels—significantly (p < 0.05) predicted a poor prognosis in the unclassified ovarian cancer patients." (PMID 30301218, 2018). "Similarly, in the ovarian cancer patients receiving taxol adjuvant therapy, the elevated mRNA levels detected by probes for DGKH (except probes 235952_at and 240145_at), FBXL7, and MFSD6 appeared to be correlated with poor outcomes." (PMID 30301218, 2018). "To estimate the clinical relevance of DGKH, FBXL7, and MFSD6 in patients with ovarian cancer, we next performed Kaplan-Meier analysis using the K-M Plotter database." (PMID 30301218, 2018). "In addition, Kaplan-Meier analysis for other DGKH and MFSD6 microarray probes using the K-M Plotter database against the unclassified ovarian cancer patients yielded similar results under the condition of PFS probability." (PMID 30301218, 2018).
pancreatic cancer (1 paper, 2020). "However, the functional roles and the clinicopathological significance of AK4 and DGKH in pancreatic cancer have never been investigated." (PMID 33194391, 2020).
cancer (3 papers, 2020 to 2025). A tumor composed of atypical neoplastic, often pleomorphic cells that invade other tissues. "DGKH depletion shifts sorafenib's effect from growth arrest to robust induction of cell death; in immunocompetent mice, combining DGKH depletion with sorafenib reduces tumour burden and depletes residual cancer stem-cell compartments." (PMID 41323031, 2025). "They show that DGKH dependent production of PA ignites mTOR activity independently of the canonical phosphatidylinositol 3-kinase-protein kinase B (PI3K-AKT) axis, thereby forging a direct mechanistic link between lipid signaling, cancer stem-cell traits and sustained mTOR activation." (PMID 41323031, 2025).
tumor (3 papers, 2023 to 2025). "Using healthy donor CD34+ cells as a reference, we detected overexpression of DGKA, DGKG, DGKD and DGKQ in tumor samples, while DGKH and DGKZ were unchanged." (PMID 37509516, 2023).
DGKH also shares sentences with these, for which no sentence is quoted: acute lymphoblastic leukemia (1 paper); attention deficit-hyperactivity disorder (1); autism (1); epilepsy (1); hepatocellular carcinoma (1); HIV-1 infection (1); infection (1); leukemia (1); lung carcinoma (1); obsessive-compulsive disorder (1); ovarian serous cystadenocarcinoma (1); pheochromocytoma (1); sarcoidosis (1); schizophrenia (1); type 2 diabetes mellitus (1); urinary stones (1); uterine carcinosarcoma (1); vascular disorder (1).